LYSET (lysosomal enzyme trafficking factor)
Description:
Required for mannose-6-phosphate-dependent trafficking of lysosomal enzymes. LYSET bridges GlcNAc-1-phosphate transferase (GNPTAB), to the membrane-bound transcription factor site-1 protease (MBTPS1), thus allowing proteolytic activation of the GNPTAB. GNPTAB is involved in the regulation of M6P-dependent Golgi-to-lysosome trafficking of lysosomal enzymes. LYSET is thus an essential factor for maturation and delivery of lysosomal hydrolases. (Microbial infection) Essential for infection by muliple viruses, including SARS-CoV-2, that utilize activated cathepsins for entry after M6P-dependent lysosomal transport.
Synonyms: GCAF; C14orf109; TMEM251; DKFZP564F1123; DMAN
Tractability: Antibody: UniProt predicts a signal peptide or a membrane-spanning region.
Gene: Protein-coding gene on chromosome 14 (93,184,951 to 93,188,463, forward strand). Ensembl gene ENSG00000153485.
Subcellular location: Golgi apparatus membrane
Subcellular location (Human Protein Atlas): Cell Junctions; Golgi apparatus
Gene Ontology:
Molecular function: protein binding
Biological process: lysosomal transport; lysosome organization; regulation of vesicle-mediated transport
Cellular component: Golgi apparatus; Golgi cisterna; Golgi membrane
Genetic constraint (gnomAD): Loss-of-function variants: 8 observed, 15.23 expected, observed/expected ratio (o/e) 0.53, 90% interval 0.31 to 0.95. The upper end of that interval is the gene's LOEUF score, 0.95, which puts it in group 4 of 6, group 1 being the genes least tolerant of losing a copy. Missense variants: 169 observed, 200.4 expected, observed/expected ratio (o/e) 0.84, 90% interval 0.74 to 0.96. Synonymous variants: 63 observed, 74.44 expected, observed/expected ratio (o/e) 0.85, 90% interval 0.69 to 1.04.
Homologues: Orthologues: chimpanzee LYSET (99% identical), dog LYSET (97% identical), macaque LYSET (97% identical), pig LYSET (96% identical), rat Lyset (94% identical), guinea pig LYSET (93% identical), mouse Lyset (93% identical), rabbit LYSET (77% identical), tropical clawed frog lyset (72% identical), zebrafish tmem251 (61% identical).
Diseases named in the same sentence as LYSET in open-access papers:
LYSET is named in the same sentence as 8 diseases in open-access papers, as found by Europe PMC text mining. Sharing a sentence is not in itself a finding about the gene and the disease. The quoted sentences say what the papers report.
mucolipidosis type II (2 papers, 2022 to 2024). Mucolipidosis II (MLII) is a slowly progressive lysosomal disorder characterized by growth retardation, skeletal abnormalities, facial dysmorphism, stiff skin, developmental delay and cardiomegaly. "Replacement of the membrane-distal residues R22, R29 or R32 by alanine and also the R39W (known to cause a mucolipidosis type II/III-like phenotype in humans) and R39A mutations had no impact on LYSET protein levels following transient transfection (Figs. EV1F and 6C)." (PMID 39587297, 2024).
mucolipidosis (1 paper, 2026). A group of inherited lysosomal storage diseases characterized by accumulation of lipids and carbohydrates in the tissues, resulting in mental disabilities and skeletal malformations. "A genome-wide CRISPR/Cas9 screen in LYSET-deficient mucolipidosis V cells revealed that disruption of ether lipid synthesis genes or peroxins markedly reduces lysosome accumulation and restores degradative capacity." (PMID 42069866, 2026).
cancer (3 papers, 2022 to 2023). A tumor composed of atypical neoplastic, often pleomorphic cells that invade other tissues. "In the nutrient-deficient TME, LYSET plays an essential role in cancer cells’ AAMR to enhance extra protein degradation for amino acid supplements." (PMID 37740762, 2023). "Therefore, LYSET plays a vital role in tumor growth and its deficiency may destroy the ability of cancer cells to tolerate amino acid deficiency." (PMID 37740762, 2023). "Although these key players essential for tumor cell proliferation in harsh TME conditions and LYSET invovled in lysosomal biogenesis have been uncovered in the latest studies, their impact on pan-cancer clinical outcomes remains unknown." (PMID 36569318, 2022). "Moreover, the latest experiment reported in the science journal shows the progressions of cancers without LYSET were inhibited because of failure in lysosomal protein degradation for amino acid supplements in nutrient-deficient TME but was not influenced in amino acid-rich conditions." (PMID 37740762, 2023).
tumor (3 papers, 2022 to 2024). "A possible potential mechanism was that the high-risk score meant enhanced LYSET-related AAMR in tumor cells that was usually observed in amino acid-deficient conditions." (PMID 37740762, 2023). "Previous studies have demonstrated that LYSET, a newly reported lysosomal enzyme transporter, could help tumor cells decompose proteins for nutrition and further accelerate tumor deterioration and proliferation." (PMID 38182713, 2024).
skeletal dysplasia (1 paper, 2025). Any Mendelian diseases that affects growth and development of the skeleton. "Notably, mutations in the human LYSET gene (TMEM251) are associated with skeletal dysplasia and severe short stature, highlighting the critical role of a functional M6P pathway in skeletal development." (PMID 40747612, 2025).
LYSET also shares sentences with these, for which no sentence is quoted: breast carcinoma (1 paper); clear cell renal cell carcinoma (1); viral infection (1).